GCLC (glutamate-cysteine ligase catalytic subunit)
Diseases named in the same sentence as GCLC in open-access papers (continued):
Sharing a sentence is not in itself a finding about the gene and the disease.
tumor (continued). "In contrast, deficiency in the cytosolic thioredoxin reductase and pharmacologic GCLC inhibition potently induces tumor regression and triggers a form of non-ferroptotic cell death regulated by cystine availability and translation." (PMID 41959261, 2026). "The mechanism behind the renal-specific increase of GCLC warrants further analysis, but may be related to varied exposure to BARD or varied Nrf2 expression in the kidneys compared to the tumor." (PMID 40881130, 2025). "Glutamate can then be metabolized either to GSH by GCLC or to 2‐OG by GLUD1 and then enter the TCA cycle.[10b] To find out which metabolic pathway(s) downstream of GLS plays a primary role in regulating tumor antigen presentation, we performed in silico metabolic flux analysis using TCGA datasets." (PMID 39482885, 2025). "BARD enhanced expression of the GCLC protein in the kidneys, but not in the tumor tissue, suggesting that BARD displayed a kidney specific antioxidant mechanism to protect against cisplatin-induced AKI through an increase in this protein." (PMID 40881130, 2025). "Notably, GCLC and HSBP1 appeared to play active roles in regulating the tumor microenvironment and immune responses in our study." (PMID 39150660, 2025). "Low levels of GCLC protein (0.1–0.2 pg/mg kidney) were detected in tumor samples regardless of treatment group following four doses of cisplatin (data not shown)." (PMID 40881130, 2025). "Finally, while the combined inhibition of GCLC with RRx-001 clearly shows promise, intravenous BSO monotherapy has yielded only modest clinical tumour responses." (PMID 40204947, 2025). "However, GCLC overexpression effectively reduces the glutamate accumulation and ferroptosis properties of CD8+ T cells, rejuvenating tumour suppressive activity." (PMID 40045458, 2025). "Using an inhibitor of GCLC, buthionine sulfoximine (BSO), we found that BSO treatment significantly decreased intracellular GSH level, increased Erastin-induced cell death and inhibited proliferation in tumor cells co-cultured with CBS-disrupted CAFs." (PMID 38389839, 2024). "Moreover, IHC analysis of CRC tissue microarray revealed GCLC upregulation in paired CRC and adjacent non-tumor tissues." (PMID 38049865, 2023). "Moreover, the promoter activities of GCLC, GSR, PRDX1, and MSRA were significantly elevated in HFD tumor cells compared to LFD cells." (PMID 35182054, 2022). "Additionally, there was a strong correlation between the expression of GCLC and the quantity of type 2 T helper cell in the LUAD tumor tissue." (PMID 36359768, 2022). "The Pharmacological prohibition of NQO1 and GCLC is a new therapeutic strategy for overcoming tamoxifen-resistance and also shows that the prediction of NQO1 as a biomarker has the significant prognostic value of tumor recurrence in BC patients." (PMID 35617355, 2022). "The levels of Nrf2 and its downstream target, GCLC, in the mammary fat pad, were not influenced by the presence of a tumor." (PMID 31752313, 2019). "Moreover, doxorubicin treatment reduces the expression of the genes GCLC and GSS, respectively, in treated tumor cells over untreated tumor cells." (PMID 24565113, 2014). "In contrast, recent research has indicated that GSH or NAC supplementation may directly reduce ROS levels and desensitized Nrf2/glutamate-cysteine ligase catalytic subunit (GCLC)-related antioxidant production pathway to promote HCC formation and tumor growth in vitro and in vivo." (PMID 39518894, 2024). "Furthermore, after transfer into LLC1-OVA tumor–bearing mice, the greatest numbers of IFN-γ–producing intratumoral CD8+ T cells were observed in mice that received A2ARi-treated GCLC-overexpressing CD8+ T cells accompanied by a decrease in tumor burden compared with other groups of mice." (PMID 38441967, 2024).
tumor (continued). "The Glutamate--cysteine ligase catalytic subunit (GCLC), the only protein annotated with the term sulfur amino acid metabolism process, had increased abundance while succinate dehydrogenase [ubiquinone] iron-sulfur subunit, mitochondrial precursor (SDHB), a tumor suppressor, had decreased abundance." (PMID 25419056, 2014). "Inhibition of central in vitro ferroptosis suppressors GPX4, GCLC, or SLC7A11 across these multiple models fails to impact established tumor growth." (PMID 41959261, 2026). "Because Nrf2D29H still promoted tumor initiation in the absence of GSR, it is likely that this is due to expression of GCLC and GCLM, Nrf2 targets that promote GSH synthesis." (PMID 40334547, 2025). "All treatment groups demonstrated low levels of GCLC protein in tumor tissues (data not shown), suggesting that BARD exhibits a preferential renal increase in GCLC which protects against cisplatin-induced kidney injury." (PMID 40881130, 2025).
infection (11 papers, 2014 to 2025). The state of being infected such as from the introduction of a foreign agent such as serum, vaccine, antigenic substance or organism. "At six hours post-infection, they reported a transient increase in Nrf2 expression and protein levels of GCLC (which is upregulated by Nrf2); this effect is probably related to an initial cellular innate immune response." (PMID 36978807, 2023). "In the present study, enhanced levels of GSH and enzymes related to its synthesis such GCLC and GS act as an indication of stress and infection in animals." (PMID 32518370, 2020). "Examination of the mRNA expression of key enzymes in the glutathione synthesis pathway displayed a marked increase (p < 0.05) in glutamate cysteine ligase (GCL) subunits GCLc and GCLm, glutathione synthetase, and glutathione reductase during the infection." (PMID 28725637, 2017). "The mRNA and protein expression of NQO1 and GCLC decreased at 5 h post-infection." (PMID 41413615, 2025). "In addition, we observed increased steady-state levels of NRF2-regulated antioxidant enzymes, heme oxygenase 1 (HO-1) and glutamate-cysteine ligase catalytic subunit (GCLC), in the presence of nitric oxide compared to vehicle-treated infections." (PMID 33323506, 2020). "HO-1 and GCLC have been observed to increase during a normal infection." (PMID 33323506, 2020). "Both GCLC and SOD-1 mRNA levels declined within 12 h of infection, reaching significantly reduced levels at 48 h (0.5-fold) and 72 h (0.49-fold), respectively, as compared to the control (p < 0.05)." (PMID 41294830, 2025). "The results demonstrated that ASFV-WT infection suppresses key genes involved in the Nrf2 signaling pathway, including GCLM, GCLC, Keap1, and NFE2L2 (Nrf2)." (PMID 39964001, 2025).
neurodegenerative disease (3 papers, 2013 to 2017). A disorder of the central nervous system characterized by gradual and progressive loss of neural tissue and neurologic function. "Abnormal expression of Nrf2, GCLc, SOD1, and SOD2 has been reported to be associated with PD and other neurodegenerative diseases." (PMID 29234413, 2017).
cardiovascular disease (1 paper, 2025). "Future studies relating arterial smooth muscle redox, GCLc, and GCLm function may provide useful insight into how calcification is induced and maintained, revealing novel therapeutic targets in cardiovascular disease." (PMID 41441180, 2025).
genetic disorder (1 paper, 2025). "Genetic analysis revealed a homozygotic change in the GCLC gene, confirming the diagnosis, and while the patient experiences chronic anemia, he maintains normal physical and neurological development, adding valuable insights to the understanding of this rare genetic disorder." (PMID 40277844, 2025).
GCLC also shares sentences with these, for which no sentence is quoted: colon cancer (4 papers); asthma (2); cardiac hypertrophy (2); cystic fibrosis (2); head and neck cancer (2); liver failure (2); nonalcoholic steatohepatitis (2); renal disease (2); Sepsis (2); acute kidney injury (1); Adult onset (1); African sleeping sickness (1); age-related macular degeneration (1); allergic disease (1); anaemia (1); astrocytoma (1); Burkitt lymphoma (1); chronic beryllium disease (1); chronic kidney disease (1); Cirrhosis (1); clear cell renal cell carcinoma (1); colon adenocarcinoma (1); coronary artery disease (1); cyst (1); dry eye (1); endometrial cancer (1); fibrosarcoma (1); fibrosis (1); glioblastoma (1); haemolytic anaemia (1).
A further 24 diseases each share a sentence with GCLC in 1 paper.